APOB (apolipoprotein B)
Diseases named in the same sentence as APOB in open-access papers (continued):
Sharing a sentence is not in itself a finding about the gene and the disease.
inflammatory bowel disease (6 papers, 2021 to 2025). A spectrum of small and large bowel inflammatory diseases of unknown etiology. "While Fusicatenibacter saccharivorans shows promise in treating inflammatory bowel disease, in our study, Fusicatenibacter saccharivorans (r = 0.4, p = 0.006) exhibited a significant positive correlation with ApoB." (PMID 40725792, 2025). "An investigation in inflammatory bowel disease patients revealed significantly lower serum cholesterol, HDL-cholesterol, apoA-I, apoC-II, apoC-III bound to apoB, phospholipids, and phospholipids not bound to apoB levels, and apoA-I immunoreactivity compared to healthy controls." (PMID 33922158, 2021).
insomnia (6 papers, 2021 to 2025). A sleep disorder characterized by difficulty in falling asleep and/or remaining asleep. "However, contrary to conventional knowledge, there does not appear to be an independent causal relationship between serum TG and ApoB levels and the risk of insomnia." (PMID 38087303, 2023). "There was no heterogeneity observed in the Q variable for TG, ApoA-1, ApoB, LPA, and insomnia (MR‒Egger Q, TG: P = 0.996, ApoA-1: P = 0.892, ApoB: P = 0.601, LPA: P = 0.339)." (PMID 38087303, 2023). "The results showed that the protein expression of ApoA 1 decreased in insomnia patients, while the expression of ApoB increased." (PMID 33511209, 2021). "Among them, the expression of F2, HP, FGA, FGB, FGG, and ApoB were upregulated in insomnia patients with wakefulness, and A2M, AHSG, APP, and ApoA1 were downregulated." (PMID 33511209, 2021). "By MVMR, the results revealed a significant causal relationship between genetic gain in ApoA-1 and LPA and risk of insomnia, but not between TG and ApoB." (PMID 38087303, 2023). "On the other hand, through Western blot experiments, we verified that the expression of FGG, FGB, FGA, APOB, F2, and HP was upregulated in insomnia patients with wakefulness compared with the control, while the expression of A2M, AHSG, and APOA1 was downregulated." (PMID 33511209, 2021). "There were no causal effects of TG or ApoB on insomnia (all P > 0.05)." (PMID 38087303, 2023). "According to relevant reports, apolipoprotein A1 (ApoA-1), apolipoprotein B (ApoB) and lipoprotein A (LPA) are closely related to the occurrence of insomnia events." (PMID 38087303, 2023). "In this study, two-sample MR and MVMR methods were used to investigate the association between serum lipid levels (including TG, ApoA-1, ApoB, LPA) and insomnia in the European population." (PMID 38087303, 2023).
liver cirrhosis (6 papers, 2018 to 2025). "In lipid metabolism, individuals carrying the PCSK7 functional gain SNP (rs236918) showed elevated plasma triglycerides (TG), total cholesterol (TC), apolipoprotein B (apoB), and increased liver cirrhosis risk." (PMID 40381082, 2025).
migraine (6 papers, 2023 to 2025). "The results of the random-effects meta-analysis suggested that LDL, APOB, and TC levels were associated with an increased risk of migraine." (PMID 38802400, 2024). "In contrast, ABCG5/ABCG8 enhancement, APOB inhibition, NPC1L1 inhibition, PCSK9 inhibition was found to be suggestively associated with higher risk of migraine." (PMID 37596566, 2023). "Interestingly, genetic variations in other lipid-lowering targets, such as APOB or PCSK9, which are associated with higher LDL cholesterol levels, have also been linked to a reduced risk of migraines." (PMID 39204161, 2024). "Nevertheless, this association did not seem to be directly linked to the total circulating levels of LDL-C, APOB, or TC, as we did not identify any significant correlation between these lipid levels and the risk of migraine." (PMID 38802400, 2024). "Our findings suggested the possibility, without confirmation, that exposure to bile acid sequestrants targeting ABCG5/ABCG8, cholesterol absorption inhibitors targeting NPC1L1, and Mipomersen targeting APOB might increase the likelihood of migraines in individuals." (PMID 37596566, 2023).
osteoporosis (6 papers, 2022 to 2026). A condition of reduced bone mass, with decreased cortical thickness and a decrease in the number and size of the trabeculae of cancellous bone (but normal chemical composition), resulting in increased fracture incidence. "Only a few cross‐sectional studies have investigated the association of apolipoprotein B (Apo B) with BMD or osteoporosis, and these findings are varied by specific sites and sex." (PMID 39468953, 2024). "It is possible to reduce the risk of osteopenia or osteoporosis by adjusting one’s diet and lifestyle according to serum apolipoprotein B concentrations at the time of the test." (PMID 36568987, 2022). "Association between Serum apolipoprotein B (g/L) and the risk of osteopenia or osteoporosis (subgroup analysis stratified by race)." (PMID 36568987, 2022). "In this study, logistic regression models were used to analyze the association between serum apolipoprotein B concentrations and osteopenia or osteoporosis." (PMID 36568987, 2022). "The non-Hispanic black group showed significant correlations in the Q1, Q2, and Q3 intervals, with each unit increase in serum apolipoprotein B concentration increasing the risk of osteopenia and osteoporosis by 160%, 133%, and 390%, respectively." (PMID 36568987, 2022). "When quartiles of apolipoprotein B concentrations were classified, each unit increase in serum apolipoprotein B concentration in the Q3 and Q4 intervals increased the risk of osteopenia or osteoporosis by 92% and 93%, respectively, in the 30–39 age group." (PMID 36568987, 2022). "Each unit increase in serum apolipoprotein B level was associated with a 67.3% increased risk of osteopenia or osteoporosis." (PMID 36568987, 2022). "The risk of osteoporosis was increased by 547% and 469% for each unit increase in serum apolipoprotein B concentration." (PMID 36568987, 2022). "Association between Serum apolipoprotein B (g/L) and and the risk of osteopenia or osteoporosis (subgroup analysis stratified by age)." (PMID 36568987, 2022). "It would be in the interest of the vast majority of patients if serum apolipoprotein B concentrations were routinely used as an indicator in clinical investigations to assess the risk of osteopenia or osteoporosis based on the results of these investigations." (PMID 36568987, 2022). "A logistic weighted regression model was used to assess the association between serum apolipoprotein B concentrations and risk of osteopenia or osteoporosis." (PMID 36568987, 2022). "When quartiles of apolipoprotein B concentrations were classified, the Mexican American group showed significant results only in the Q4 interval, with each unit increase in serum apolipoprotein B concentrations associated with a 199% increase in the risk of osteopenia or osteoporosis." (PMID 36568987, 2022). "Association between Serum apolipoprotein B (g/L ) and the risk of osteopenia or osteoporosis." (PMID 36568987, 2022). "Association between Serum apolipoprotein B (g/L) and and the risk of osteopenia or osteoporosis." (PMID 36568987, 2022). "Therefore, in the present study, we attempted to find a new indicator of apolipoprotein B as a predictor of changes in bone mineral density and the risk of reduced bone mass or osteoporosis." (PMID 36568987, 2022). "The results of Model 3 (OR, 1.673; 95% CI, 1.067, 2.624; p = 0.025) in the logistic regression model analysis showed that serum apolipoprotein B concentration, a continuous variable, was positively and significantly associated with the risk of osteopenia or osteoporosis." (PMID 36568987, 2022). "We demonstrated not only the correlation between serum apolipoprotein B concentration and bone mineral density, but also the correlation between changes in serum apolipoprotein B concentration on the risk of osteopenia or osteoporosis." (PMID 36568987, 2022).
osteoporosis (continued). "After stratification by age, serum apolipoprotein B concentrations, and the risk of lumbar spine BMD, osteopenia, and osteoporosis was correlated to varying degrees in different age groups." (PMID 36568987, 2022). "The present study is the first to examine the association between serum apolipoprotein B concentrations and BMD and the risk of osteopenia or osteoporosis." (PMID 36568987, 2022). "Stratified population analyses were used to assess differences in serum apolipoprotein B concentrations and risk of lumbar spine BMD and osteopenia or osteoporosis by sex, age group, and ethnicity." (PMID 36568987, 2022). "In this cross-sectional study, a nationally representative US population aged 20–59 years was used to examine the association between serum apolipoprotein B and lumbar spine BMD and osteopenia or osteoporosis." (PMID 36568987, 2022). "The primary objective of this study was to examine the association between apolipoprotein B and lumbar spine BMD and the risk of osteopenia or osteoporosis." (PMID 36568987, 2022). "Therefore, the purpose of this study was to determine the association between serum apolipoprotein B concentrations and lumbar spine BMD in adults aged 20–59 years and to predict its association with risk of osteopenia or osteoporosis." (PMID 36568987, 2022). "Our study showed a significant negative association between serum apolipoprotein B concentration and lumbar spine BMD in the total population, and a significant positive association with the risk of osteopenia or osteoporosis." (PMID 36568987, 2022). "When stratified by race, serum apolipoprotein B concentrations were significantly negatively associated with lumbar BMD and positively associated with risk of osteopenia or osteoporosis in Mexican American and non-Hispanic black populations." (PMID 36568987, 2022). "After stratification by age, the negative association between serum apolipoprotein B concentrations and lumbar BMD and the positive association with risk of osteopenia or osteoporosis was more significant in the 30–39 and 50–59 years age groups." (PMID 36568987, 2022). "The negative correlation between serum apolipoprotein B concentration and lumbar spine BMD and the positive correlation between the risk of osteopenia or osteoporosis were more pronounced in the 30–39 years and 50–59 years age groups." (PMID 36568987, 2022). "The association of serum apolipoprotein B concentration with lumbar spine BMD and risk of osteopenia or osteoporosis was significant in male, but not in female." (PMID 36568987, 2022). "After stratifying the groups by ethnicity, there was a significant negative association between serum apolipoprotein B concentrations and lumbar spine BMD, and a significant positive association between the risk of osteopenia or osteoporosis in the Mexican American and non-Hispanic black groups." (PMID 36568987, 2022).
ovarian carcinoma (6 papers, 2017 to 2025). A malignant neoplasm originating from the surface ovarian epithelium. "Additionally, a significant association was reported between increased APOB and high-grade ovarian cancer." (PMID 38067270, 2023). "This study involved samples from newly diagnosed high-grade ovarian cancer cases and suggested that increased APOB levels might be indicative of a favorable prognosis." (PMID 38067270, 2023). "Some epidemiological studies have provided evidence that links the concentration of APOA1, APOB, HDL, LDL, and TG to the risk of OC, but we further analyzed the effect on the subtypes of ovarian cancer to rule out false-positive results." (PMID 36557213, 2022).
periodontitis (6 papers, 2015 to 2025). An acute or chronic inflammatory process that affects the tissues that surround and support the teeth. "This review highlights the role of oxidative stress, oxidised low-density lipoprotein (oxLDL), and apolipoprotein B (apoB) as molecular links between periodontitis and metabolic disorders." (PMID 41465350, 2025). "Another cross-sectional study also showed that in patients with chronic periodontitis, the level of apolipoprotein B (apo B) in gingival crevicular fluid in the infected area was higher than that in the healthy area." (PMID 37583432, 2023). "Individuals carrying APOB-rs1042031-CT (mainly women and never smokers) had a lower risk of developing periodontitis and T2DM (T2DM+P); altogether, this genotype was related with healthier glycemic, lipid, and periodontal parameters." (PMID 34805411, 2021). "In addition, apoL-1 correlated with BOP, apoB/apoA-I ratio and apoC-II further suggesting an involvement in the inflammation in periodontitis." (PMID 30842338, 2019). "P. gingivalis-induced fragmentation of apoB, and LDL from periodontitis patients, lead to increased uptake by macrophages, resulting in foam cell formation." (PMID 30842338, 2019).
peripheral vascular disease (6 papers, 2008 to 2025). Any disorder affecting blood flow through the veins or arteries outside of the heart. "Rs7575840 in 6.5kda upstream of ApoB gene, rs11591147 in PCSK9 gene and rs9644862 in the CDKN2B-AS1 (or named ANRIL; p15AS; PCAT12; CDKN2BAS; CDKN2B-AS; NCRNA00089) gene were illustrated to mostly influence the risk of intestinal vascular diseases." (PMID 39991491, 2025). "More than 75% diabetic patients with peripheral vascular disease treated at primary health care level achieved adequate targets for diastolic blood pressure, cholesterol, LDL-cholesterol and triglycerides levels (also apolipoprotein B values)." (PMID 18671870, 2008).
acne (5 papers, 2018 to 2025). An inflammatory process of the sebaceous glands which is characterized by comedones, nodules, papules and/or pustules on the skin. "Compared with patients with the H1H1 genotype, patients with the H2 allele (H1H2 + H2H2) in -317H1/H2 polymorphism had lower acne grade score and the ratio of apoB-PAF-AH to H-PAF-AH (P < 0.05)." (PMID 29636060, 2018). "In this study, we found that compared with H1H1 homozygotes, the H2 allele was associated with lower ratio of apoB-PAF-AH to H-PAF-AH and acne grade score in patients with PCOS." (PMID 29636060, 2018). "In addition, we found a higher acne grade score and an increased ratio of apoB-PAF-AH to H-PAF-AH activity in patients carrying the H1H1 genotype of the -317H1/H2 polymorphism compared with patients carrying the H2 allele." (PMID 29636060, 2018). "However, the other three LDL-lowering therapies, targeting HMGCR, NPC1L1, and APOB, showed no significant causal effect on acne vulgaris risk." (PMID 38903813, 2024).
Anxiety (5 papers, 2015 to 2024). Intense feelings of nervousness, tension, or panic often arise in response to interpersonal stresses. "This anxiety-like behaviour may result from LPS-induced aberrant astrocyte and oligodendrocyte differentiation in the brain, potentially through immune responses mediated by the ApoB/E receptor signalling axis." (PMID 37592237, 2023).
bipolar disorder (5 papers, 2010 to 2025). A disorder of the brain that causes unusual shifts in mood, energy, activity levels and the ability to carry out day-to-day tasks. "For example, a previous study in unipolar and bipolar depression found cognitive abilities were associated with altered levels of Apolipoprotein B (ApoB)." (PMID 38467624, 2024). "ApoA1 (a major component of high-density lipoprotein (HDL)) and ApoB (a major component of low-density lipoprotein (LDL)) are thought to be involved in the inflammatory processes and neuroprogression associated with bipolar disorder." (PMID 41220462, 2025). "In contrast, ApoB levels are significantly higher in patients with bipolar disorder compared with those with unipolar disorder, making ApoB a potential biomarker for distinguishing between the two." (PMID 37592237, 2023). "In terms of metabolic indicators, patients with bipolar disorder and comorbid MAFLD showed significantly higher levels of glucose, ALT, ALP, TC, ApoB, triglycerides, and GGT, while exhibiting slightly lower levels of ApoA1 and significantly lower levels of HDL." (PMID 40810071, 2025).
cardiomyopathy (5 papers, 2020 to 2025). A disease of the heart muscle or myocardium proper. "Other studies focusing on a Han population found an association between a prognosis of heterogeneous cardiomyopathy with SNPs associated with LGALS3, AGCT, SLC25A13, HRG, APOB, SOD3, SYNM, and TLN2." (PMID 34572079, 2021). "The regulatory roles of other enriched genes in cardiomyopathy networks (including SYNE2, APOB, XIRP1, ALPK3, and LRPPRC) are not clear." (PMID 34236536, 2021).
cholelithiasis (5 papers, 2015 to 2025). The presence of crystallized deposits forming in the gallbladder or biliary tree, primarily composed of cholesterol, bilirubin, and bile. "We identified that LDL-C and apolipoprotein B mediate the effects of thyroid function on the cholelithiasis risk." (PMID 37065749, 2023). "LDL-C and apolipoprotein B were also correlated with an elevated risk of cholelithiasis in our large-scale MR study." (PMID 37065749, 2023). "The IVW method revealed that apolipoprotein B was correlated with an elevated risk of cholelithiasis (OR: 1.255, 95% CI: 1.027–1.535, P = 0.027)." (PMID 37065749, 2023). "We demonstrated that FT4, LDL-C, and apolipoprotein B had significant causal effects on cholelithiasis, with evidence that LDL-C and apolipoprotein B mediated the effects of FT4 on cholelithiasis risk." (PMID 37065749, 2023). "Additionally, elevated levels of LDL-C and apolipoprotein B were also significantly associated with an increased risk of cholelithiasis." (PMID 37065749, 2023). "Finally, using the two-step MR analysis, we identified that LDL-C and apolipoprotein B acted as mediators of the causal pathway from FT4 levels to cholelithiasis risk." (PMID 37065749, 2023). "In conclusion, we demonstrated that FT4, LDL-C, and apolipoprotein B had significant causal effects on cholelithiasis, with evidence that the LDL-C and apolipoprotein B mediated the effects of FT4 on cholelithiasis risk." (PMID 37065749, 2023). "The present analysis revealed that apolipoprotein B and LDL-C mediated the effects of thyroid function on cholelithiasis risk." (PMID 37065749, 2023). "Thyroid function and the risk of cholelithiasis are mediated by LDL-C and apolipoprotein B. LDL-C and apolipoprotein B had 17.4% and 13.5% of the mediatory effects, respectively." (PMID 37065749, 2023). "Apolipoprotein B (OR: 1.255, 95% CI: 1.027–1.535, P = 0.027) and low-density lipoprotein cholesterol (LDL-C) (OR: 1.354, 95% CI: 1.060–1.731, P = 0.016) were also correlated with an elevated risk of cholelithiasis." (PMID 37065749, 2023). "The negative mediation effects observed for the ratio of apolipoprotein B to apolipoprotein A1, phospholipid levels in VLDL, and triglyceride levels in large LDL and IDL suggest a complex interplay between lipid metabolism, BMI, and cholelithiasis risk." (PMID 39747165, 2025).
colon cancer (5 papers, 2018 to 2024). "In colon cancer cells, APOB also participates in the transport of vitamin E." (PMID 38212768, 2024).
gestational diabetes (5 papers, 2013 to 2024). Carbohydrate intolerance first diagnosed during pregnancy. "Age, pre-pregnancy BMI, FPG, PT, INR, APTT, FIB, TT, D-Dimer, TC, TG, LDL-C, sdLDL-C, APOB, and APOE were all predictors of gestational diabetes in the study population (P < 0.05)." (PMID 35387184, 2022).